REST (RE1 silencing transcription factor)
Diseases named in the same sentence as REST in open-access papers (continued):
Sharing a sentence is not in itself a finding about the gene and the disease.
breast carcinoma (continued). "Using a similar molecular-profiling strategy, we have identified a previously unrecognized subset of breast cancers in which the tumor suppressor gene REST is lost, which display a highly aggressive disease course." (PMID 20548947, 2010). "Non-targeting control shRNA expressing cells showed strong nuclear REST staining, whereas the REST knockdown cells show a severely depleted nuclear REST stain, suggesting specificity for the antibody at levels of REST observed in breast cancer cells." (PMID 20548947, 2010). "Using this gene signature as well as an immuno-histochemical screen, we show here that an aggressive subset of breast cancers lack functional REST (“REST–less tumors”), instead, often expressing the truncated REST splice variant REST4." (PMID 20548947, 2010). "To test the specificity of the REST antibody, we utilized the REST-expressing breast cancer cell line MCF7." (PMID 20548947, 2010). "Moreover, the inhibition of STP axis components resulted in high expression of REST proteins and impairment of TNBC transformation, which indicated the tumor-suppressive role of REST in breast cancer cell lines." (PMID 40006989, 2025). "Additionally, in breast cancer, a regulatory role of REST on MMP24 expression, a gene that is increased in PCa, has been proposed." (PMID 38542313, 2024). "Similarly, prior studies have indicated a relationship between REST and estrogen signaling in breast cancer cell lines and in REST conditional knockout mice with uterine pathology, such as leiomyomas, which support our findings." (PMID 39273639, 2024). "REST has been linked to several cancers, including colon, small cell lung, and breast cancer as a putative tumor suppressor and decreased expression of REST may lead to cancer." (PMID 39273639, 2024). "Additionally, aberrant splicing of REST leading to the expression of REST4, a truncated form of REST, has been reported in breast cancer samples and in the hippocampus." (PMID 35177031, 2022). "We found REST target genes are frequently dysregulated in different types of cancers, including breast cancer, without a concurrent loss of REST mRNA expression." (PMID 35177031, 2022). "We find REST alters the estrogen signaling pathway in hormone responsive breast cancer cells." (PMID 35177031, 2022). "We then utilized gene knockdown in MCF-7 cells in the presence or absence of steroid hormones estrogen and/ progesterone followed by RNA sequencing, as well as chromatin immunoprecipitation and PCR in an attempt to understand the tumor suppressor role of REST in breast cancer." (PMID 35177031, 2022). "Therefore, we consider REST as an attractive target for therapy in breast cancer and other oncogenic diseases." (PMID 35177031, 2022). "We wanted to confirm that REST directly regulates MMP24 in breast cancer cells." (PMID 35177031, 2022). "REST knockdown in breast cancer cells leads to significant upregulation of CEMIP and MMP24." (PMID 35177031, 2022). "Since REST plays a crucial role in the pathogenesis of uterine fibroids and its steroid hormone response (unpublished data), we wanted to investigate if similar mechanisms of steroid hormone sensitivity and tumor pathogenesis exist in breast cancer." (PMID 35177031, 2022). "TCGA data was analyzed for the expression of REST target genes in breast cancer patient samples." (PMID 35177031, 2022). "Since REST is downregulated in breast cancer, this results in an increased intratumoral SP-level." (PMID 34336669, 2021). "REST is a major tumor suppressor in colon, lung and breast cancers and may be key to the neuro-endocrine character of some of these tumors." (PMID 23673719, 2013). "Additionally, the alternative splicing observed in REST–less breast cancer is an attractive therapeutic target." (PMID 20548947, 2010). "Therefore, we believe that the signaling pathways regulating potentially reversible REST4 splicing represent an attractive pharmacological opportunity for combating REST–less breast cancer." (PMID 20548947, 2010).
breast carcinoma (continued). "In fact, in other cancer types such as breast cancer, REST loss of function and the presence of REST4 transcript variant correlate with target gene dysregulation and tumour aggressiveness, whereas in colorectal cancer REST is frequently deleted and this is associated with malignancy transformation." (PMID 37301955, 2023). "As REST is the only repressor among this group, and because REST degradation is known to promote TNBCs, we examined the status of REST, by comparing the normal and primary breast cancers and found that, REST is significantly downregulated in primary breast cancers compared to normal specimens." (PMID 30335837, 2018). "Therefore, to rule out the possibility that discrepancy between both studies is due to the use of different cell lines, we tested whether REST protein expression and turnover were differently regulated in the breast cancer cell line MDA-MB-231." (PMID 28570664, 2017). "For instance, REST is a crucial regulator for acquiring EMT-like and stemness, and TRPS1 positively correlates with E-cadherin and β-catenin expression in ERα-positive breast cancer cells." (PMID 37190063, 2023). "We next sorted the RNASeq data of primary breast cancer patients based on RESTlow and RESThigh groups with 300 patients for each group and examined the expression patterns of TBP, CEBPB, REST, CTCF, RAD21 and SMC3 in addition to unsorted patient dataset." (PMID 30335837, 2018). "Treatment of breast cancer cells with 5-Aza/TSA derepressed miR-205 and reduced HMGB3 mRNA while knockdown of the transcriptional repressor NRSF/REST, reduced miR-205 and increased HMGB3." (PMID 24098490, 2013). "The aberrant expression of sREST mRNA, but not of full-length REST mRNA, is a hallmark of the NE phenotypes of SCLC and PCa and possibly of aggressive breast cancer types." (PMID 39377066, 2024). "When broken down into breast cancer subtypes based on invasiveness including normal like, invasive ductal carcinoma (IDC), and ductal carcinoma in situ (DCIS) we see differential expression of a novel set of REST target genes across all the subtypes." (PMID 35177031, 2022). "Our study showed REST could directly bound to DYRK1A promoter, initiating the transcription, and previous research proved REST was an tumor suppressor in breast cancer cells." (PMID 24901999, 2014). "Remarkably, a subset of tumors from all histological classes of breast cancer stained negative for REST C-terminus, and all classes showed a worse prognosis without REST." (PMID 20548947, 2010). "In this report we describe the generation of such a signature for the tumor suppressor RE1 Silencing Transcription Factor (REST Enterez GeneID 5978), also known as Neuron Restrictive Silencing Factor (NRSF), and the identification of this signature in breast cancer." (PMID 20548947, 2010). "Additionally, in spite of finding putative REST gene signatures in breast cancers, direct transcriptional regulation of genes aberrantly expressed in RESTless breast cancers has not been investigated." (PMID 35177031, 2022). "However, it has been shown that tumor cells also express SP, and SP levels are elevated in breast cancer due to the lacking inhibitory effect of the RE1-silencing transcription factor (REST) in SP-expression." (PMID 34336669, 2021). "Our results reveal regulatory interactions among REST, REST-003, and a cancer cell-specific splicing activator (SRRM3) that may coordinate gene regulation required for development of the invasive cancer phenotype in breast cancer." (PMID 26053433, 2015). "While the loss of REST has previously been shown to increase MMP24 expression in breast cancer cells, transcriptional regulation of MMP24 by REST has not been studied so far." (PMID 35177031, 2022).
glioma (30 papers, 2009 to 2025). A benign or malignant brain and spinal cord tumor that arises from glial cells (astrocytes, oligodendrocytes, ependymal cells). "Survival analysis indicated that patients with high SLC40A1 expression had shorter survival times, suggesting its association with glioma malignancy and relevance to erianin and REST-related ferroptosis." (PMID 39039049, 2024). "High expression of REST was significantly associated with worse overall survival, progression-free interval, and worse disease-specific survival in glioma patients." (PMID 38609948, 2024). "We found that sites differentially methylated in gliomas appeared within 47 REST ChIP-seq peaks, out of which 32 were associated with REST-repressed targets, while 15 with REST-activated targets." (PMID 38711090, 2024). "The expression and function of predicted upstream miRNAs at REST and their association with glioma malignancy and migration were also confirmed in glioma cell lines." (PMID 36810892, 2023). "MiR-9-5p and miR-105-5p were the potential upstream regulatory miRNAs of REST in glioma and their upregulation were positively linked to patients’ prognosis." (PMID 36810892, 2023). "In the current study, miR-9-5p and miR-105-5p were identified as the potential upstream regulatory miRNAs of REST in glioma and their upregulation were positively linked to patients’ prognosis." (PMID 36810892, 2023). "REST was highly expressed and associated with poorer overall survival and disease-specific survival in glioma and some other tumors." (PMID 36810892, 2023). "Kaplan–Meier analyses in CGGA cohort also suggested an association between high REST expression and poor OS in glioma." (PMID 36810892, 2023). "We sought to clarify the clinical relationship between REST/NRSF expression and the prognosis of glioma and explore the REST-associated competitive endogenous RNA (ceRNA) network in glioma." (PMID 34859007, 2021). "Higher REST expression was significantly associated with worse overall survival, progression-free interval, and worse disease-specific survival in glioma patients." (PMID 34859007, 2021). "REST expression was significantly higher in glioma than that in normal samples, and was associated with clinical characteristics." (PMID 34859007, 2021). "Interestingly, within the LGGs, REST expression was significantly higher in IDH1/2 mutated (IDH-MUT) gliomas than in wild type samples (IDH-WT) (two-sample Wilcoxon test)." (PMID 38711090, 2024). "REST knockdown differently affected cell invasion of the parental or IDH1-mutated glioma cells." (PMID 38711090, 2024). "The noncoding RNA (ncRNA)-associated regulation of REST expression was also explored in glioma." (PMID 36810892, 2023). "Moreover, REST expression was positively associated with immune cell infiltration and biomarkers of immune cells in glioma, as well as the immune checkpoints PD1, PD-L1, and CTLA-4, indicating its impact on tumor immunity." (PMID 36810892, 2023). "Therefore, further study is needed to validate the prognostic value of REST and investigate the underlying molecular mechanisms in tumorigenesis and development of glioma." (PMID 36810892, 2023). "More specifically, they found that an important methylation feature (cg15072976) overlaps with the RE1 Silencing Transcription Factor (REST) binding site, intersect with the REST binding motif in human U87 glioma cells, and shows positive association with patient survival time." (PMID 36418365, 2022). "Additionally, in the glioma cohort, positive associations between 13-gene scores and REST (rho = 0.39; P < 0.0001) or SUZ12 (rho = 0.17; P < 0.0001) profiles were observed." (PMID 31523055, 2019). "High REST expression in G4 gliomas might be associated with a strong repression of these genes." (PMID 38711090, 2024). "Therefore, we analyzed the DE-lncRNA and DE-miRNAs associated with REST expression in gliomas; these DE-ncRNAs may regulate or be regulated by REST either directly or indirectly." (PMID 34859007, 2021).
glioma (continued). "However, the clinical relevance, gene function, and the regulatory mechanism of REST-associated ceRNA network remain unknown in glioma." (PMID 34859007, 2021). "REST expression was found to be significantly high in patients with glioma, a common type of tumors of the nervous system." (PMID 40006989, 2025). "qPCR revealed significantly higher REST expression in glioma compared to normal brain tissue in our cohort, with the highest expression in GBM correlating with increased WHO grades." (PMID 39039049, 2024). "Taken together, these data and the results of the previous section show that REST inhibits the expression of HAR1A in glioma cells, and that REST appears to be essential for the proliferation of GBM cells." (PMID 39602392, 2024). "Higher REST expression predicts worse prognosis in low-grade gliomas (the opposite is true for HAR1A)." (PMID 39602392, 2024). "Intriguingly, REST is known to have an oncogenic role in gliomas, through the repression of tumour-suppressor genes." (PMID 39602392, 2024). "For instance, REST loss in T98G cells led to a reduction in NEDD9 expression, a marker of glioma invasion potential, and an increase in BEX1 expression, a tumor suppressor gene in malignant glioma." (PMID 38609948, 2024). "We performed a comprehensive study to identify transcriptional targets of REST and unravel REST regulatory networks in U87 glioma cells with a different IDH status." (PMID 38711090, 2024). "Comparative analysis between GTEX and TCGA glioma databases revealed significantly elevated expression of REST in gliomas." (PMID 39039049, 2024). "REST ChIP-seq data on human U87 glioma cells integrated with the results of transcriptomic changes in REST depleted U87 cells allowed us to define direct and indirect REST targets." (PMID 38711090, 2024). "In summary, these results suggest that REST is the target of erianin in regulating gliomas, overexpressed in glioma and correlating with poor patient prognosis." (PMID 39039049, 2024). "The expression of REST was the lowest in normal brain tissue and the highest in the WHO grade 4 gliomas, with REST expression increasing with glioma malignancy from G2, through G3 to G4." (PMID 38711090, 2024). "REST expression in glioma was positively correlated with immune cell infiltration and the expression of immune checkpoints, including PD1/PD-L1 and CTLA-4." (PMID 38534769, 2024). "Recent studies have highlighted REST as an oncogenic gene and marker of a poor prognosis in glioma, with its high expression potentially influencing the tumor microenviroment (TME)." (PMID 38534769, 2024). "Initially, almost 70,000 REST and KAISO motif sites were found within REST ChIP-seq peaks in glioma cells, and 601 of them were differentially methylated among gliomas, which accounts for 0.9% of the all identified REST and KAISO motif sites." (PMID 38711090, 2024). "We aimed at defining how REST modulates gene activation and repression in the context of the IDH mutation-related phenotype in gliomas." (PMID 38711090, 2024). "To find REST dependent genes in glioma cells with different IDH1 status, we performed siRNA mediated knockdown of REST (siREST) in IDH-WT and IDH-MUT U87 glioma cells." (PMID 38711090, 2024). "In this study, we have shown that HAR1A is negatively regulated by REST in glioma cells, and that the expression of these two molecules has an opposite prognostic significance in glioma patients." (PMID 39602392, 2024). "In mice, expression of REST in glioma stem cells (GSCs) was negatively correlated with survival and considered as a critical factor in maintenance of their self-renewal." (PMID 38711090, 2024). "Our results confirmed that HAR1A and HAR1B are negatively correlated with REST expression in pediatric gliomas." (PMID 39602392, 2024). "We confirmed that genes selected as REST targets in cultured glioma cells, were co-expressed in a REST dependent manner in TCGA glioma datasets." (PMID 38711090, 2024).
glioma (continued). "Our findings contribute to better predictions of glioma patient survival based on DNA methylome and transcriptome evaluation, and suggest a potential of targeting REST in glioma therapy." (PMID 38711090, 2024). "To analyze the relationship between HAR1A and HAR1B with REST in gliomas, we began by correlating their RNA expression in lower grade gliomas and glioblastoma, using the Cbio Portal." (PMID 39602392, 2024). "We show that REST can impact the prognosis and progression of gliomas via different mechanisms, including enhanced cell proliferation, repression of neural-differentiation genes and potentially increased migration." (PMID 39602392, 2024). "siRNA mediated knockdown of REST in established human U-87 MG and U-251 glioma cells reduced cell proliferation and migration." (PMID 38711090, 2024). "Knockdown of REST had a different impact on glioma invasion depending on the IDH phenotype, which is connected to DNA hypermethylation phenotype." (PMID 38711090, 2024). "Considering the ongoing development of REST small molecule inhibitors for glioma treatment, our results have therapeutic relevance." (PMID 39602392, 2024). "Several studies reported that REST acts as an oncogene in gliomas, promoting cell proliferation and invasion." (PMID 38711090, 2024). "The methylome data in the glioma Atlas are dense, thus we were able to calculate TF motif site mean methylation and correlate it with REST target expression." (PMID 38711090, 2024). "The motifs identified in both REST-repressed and activated targets included E2F transcription factor family motifs, which is a classic TF involved in glioma progression." (PMID 38711090, 2024). "Otherwise, the REST mRNA expression level was higher in non-1p/19q codeletion or IDH status-WT gliomas in both TCGA cohort (P < 0.001) and CGGA cohort (P < 0.001)." (PMID 36810892, 2023). "We observed that REST expression was positively correlated with immune infiltration levels and the expression of immune checkpoint markers in glioma." (PMID 36810892, 2023). "To further verify the expression level of REST in glioma, we tested REST mRNA expression in the GEO dataset between oligodendroglioma (glioma 53 and normal 28) and astrocytoma (glioma 123 and normal 28)." (PMID 36810892, 2023). "Our founding showed that high expression of REST was positively linked to PD1, PD-L1, and CTLA-4 in glioma." (PMID 36810892, 2023). "The REST expression level in glioma is also positively correlated with the infiltration level of cancer-associated fibroblasts based on the EPIC, MCPCOUNTER and TIDE algorithms (P < 0.001)." (PMID 36810892, 2023). "More basic experiments and large clinical trials aimed at the carcinogenetic study of REST in glioma will be needed in the future." (PMID 36810892, 2023). "After performing correlation analysis, expression analysis, survival analysis, and experiments in vitro, we identified miR-105-5p and miR-9-5p as the potential upstream miRNAs of REST in glioma." (PMID 36810892, 2023). "MicroRNAs (miRNAs) contributing to REST overexpression in glioma were identified by a combination of a series of in silico analyses, including expression analysis, correlation analysis, and survival analysis." (PMID 36810892, 2023). "Increased REST expression was reported to promote tumour progression in glioma, suggesting its role as an oncogene in brain cancer." (PMID 37301955, 2023). "MiR-105-5p and miR-9-5p were identified as the most potential upstream miRNAs of REST in glioma patient cohort and experiments in vitro." (PMID 36810892, 2023). "REST expression has been previously found to be correlated with immune cell infiltration and immune checkpoints in glioma, and its expression has been suggested as a biomarker of poor prognosis in glioma." (PMID 37533331, 2023).